INS (insulin)
Diseases named in the same sentence as INS in open-access papers (continued):
Sharing a sentence is not in itself a finding about the gene and the disease.
Obesity (continued). "Moreover, the study revealed that CerS6Δ/Δ mice were protected from diet-induced obesity and had improved whole-body glucose metabolism and hepatic insulin signaling." (PMID 33815291, 2021). "Obesity is a crucial factor involved in insulin-resistant development." (PMID 34394985, 2021). "The immune dysregulations include increased levels of inflammatory markers such as C - reactive protein (CRP), interlukin-6 (IL-6), tumour necrosis factor alpha (TNF alpha), and other cytokines indicating insulin and leptin resistance, obesity, inflammation, and higher rates of metabolic syndrome." (PMID 34895175, 2021). "However, there are some studies that argue for stimulatory action of ECs and synthetic CB1R agonists in insulin secretion, at least with supraphysiological levels, that possibly plays a role in hyperinsulinemia as seen in obesity." (PMID 34290671, 2021). "However, we did not demonstrate that dehydrogenase activity in skeletal muscle or adipose tissue is substantially upregulated in obesity or by insulin." (PMID 33270115, 2021). "Moreover, 1-deoxynojirimycin, known for anti-hyperglycemic and anti-obesity effects, was found to increase glucose tolerance, insulin signaling and reduction of the white adipose tissue in HFD-fed mice." (PMID 33806509, 2021). "From a mechanistic perspective, obesity can drive oncogenesis through the decreased secretion of adiponectin and the chronic production of adipokines, insulin, insulin-like growth factor, inflammatory cytokines and tumour necrosis factor including IL-6 and TNFa." (PMID 34014795, 2021). "Further, an acute dose of 24 g inulin in men with obesity decreased postprandial (0–3 h) plasma glucose (glucose iAUC, 8.12 ± 3.07 vs. 46.97 ± 3.57 mmol/L, p = 0.002) and insulin (insulin iAUC, 1494 ± 81 vs. 3523 ± 161 mU/L, p = 0.001) while increasing fat oxidation (p < 0.05)." (PMID 34684471, 2021). "In addition, the effect of other obesity-related signaling molecules on lung cancer development such as insulin, insulin-like growth factor-1, adiponectin, steroid hormones, and cytokines needs to be elucidated." (PMID 33708630, 2021). "Interestingly, it has been reported that BACE1 suppression decreases body weight, protects against diet-induced obesity and enhances insulin sensitivity in mice." (PMID 34015524, 2021). "Only one study has investigated the effects of taurine supplementation in obese fathers, and showed that paternal intake of this specific amino acid partially reversed the deleterious effects of paternal obesity on insulin secretion and islet morphology in F1 offspring." (PMID 34069853, 2021). "Some studies have shown that P. copri were involved in occurrence of obesity through promoting the biosynthesis of branched-chain amino acids to induce insulin resistance and stimulating the secretion of inflammatory factors to trigger or aggravate the host’s inflammatory response." (PMID 33717692, 2021). "The link between increased pro-inflammatory immune cell populations and reduced insulin sensitivity in IECs in obesity could provide new insight into the development of insulin resistance and T2D." (PMID 35145486, 2021). "Concerning overweight/obesity, general population data suggests that sleep restriction is positively related to subjective hunger, caloric intake, and weight gain and negatively related to insulin sensitivity." (PMID 33561176, 2021). "The other 2 associations had a moderate quality of evidence, namely, the use of zero-calorie ADF for the reduction of fat mass and the 5:2 diet for the reduction of fasting insulin in adults with overweight or obesity compared with continuous energy restriction and/or regular diet." (PMID 34919135, 2021). "Inactivation of kiss1r in mice results in obesity and diabetic phenotype, and kisspeptin and its receptor are expressed in metabolic tissues (e.g., fat, liver and pancreatic tissues) and likely plays a role in regulating insulin secretion." (PMID 34300220, 2021).
Obesity (continued). "In 2010, Zhou and colleagues were the first researchers who indicated that the NLRP3 inflammasome may impact the regulation of adiposity and insulin sensitivity in the course of obesity." (PMID 34070553, 2021). "Indeed, mice with a low Scd1 gene expression display enhanced energy expenditure, decreased body adiposity, increased insulin sensitivity, and are resistant to diet-induced obesity." (PMID 33918417, 2021). "Obesity-related IR implicates the PI3-K pathway that confers the metabolic effects of insulin." (PMID 33430419, 2021). "While varying in diet compositions and duration of exposure, many studies have reported relatively consistent findings where offspring born to dams with pregestational obesity have hypertension, endothelial dysfunction, increased adiposity, and decreased insulin sensitivity." (PMID 34108935, 2021). "Maternal pre-pregnancy obesity may contribute to macrosomia due to increased insulin resistance, which leads to enhanced hepatic glucose production and cause high fetal glucose and insulin concentrations." (PMID 33224106, 2020). "The five obesity genes uncovered could be novel genes that play roles in the etiology of TC through the modulation of INS levels." (PMID 33240576, 2020). "Unlike leptin and insulin, obesity does not seem to cause peripheral resistance to PYY, suggesting that the observed increases in older adults are likely to exert anorectic effects." (PMID 31432431, 2020). "One potential mechanism may involve sexually dimorphic changes in the central actions of insulin and leptin with obesity." (PMID 32160920, 2020). "Moreover, the waist circumference and serum insulin levels in subjects with obesity were found to be reduced after 2 weeks of GLN supplementation." (PMID 33086562, 2020). "On one hand, perturbations in gut bacterial homeostasis might lead to increased intestinal permeability, low grade inflammation or insulin resistance and obesity, the last two of which are risk factors for developing AD." (PMID 32508799, 2020). "Our data suggests that the harmful effects of obesity on insulin secreting cells may be mediated, at least partially, by alterations in the miRNA expression pattern." (PMID 32286278, 2020). "Furthermore, Ucp2MGKO mice were protected from diet-induced obesity; their food intake was reduced, energy expenditure increased, and insulin sensitivity improved compared to control mice on HFD." (PMID 33240218, 2020). "While a definite answer to this question is not readily available, several sex/gender-related differences in energetic homeostasis should be highlighted: organ-specific insulin resistance, potential intersection with ethnicity and responses to fasting, hypoglycemia, exercise, obesity and aging." (PMID 32354182, 2020). "Elevated insulin and, thus, reduced ketones are an essential feature of human obesity." (PMID 32872407, 2020). "AKT is involved in insulin signaling and is altered in obesity status." (PMID 32408716, 2020). "In our study, we successfully established a rat model of PCOS with the characteristics of polycystic ovaries, obesity, irregular estrous cyclicity, hyperandrogenism, increased plasma insulin levels, decreased plasma SHBG levels, and increased LH concentrations." (PMID 32733580, 2020). "The overload of brain iron could result in insulin resistance together with cognitive decrease in animal obesity models and human obesity models." (PMID 33062715, 2020). "Obesity increased plasma glucose and insulin and decreased irisin and FGF-21." (PMID 32230849, 2020). "Although physiological activation of AMPK in peripheral tissues promotes FA oxidation and insulin sensitivity, in the pathological inflammatory state, chronic activation of AMPK activity in the hypothalamus causes obesity by inducing hyperphagia in both humans and rodents." (PMID 32825115, 2020).
Obesity (continued). "Furthermore, through microRNA modulation, they attenuated key metabolic alterations, including insulin resistance and lipid anomalies, in animal models of obesity." (PMID 33261062, 2020). "Recent studies suggest that the PPP might serve as a novel and promising target for modulating obesity-induced inflammation and insulin sensitivity in different tissues." (PMID 32582032, 2020). "Biological mechanisms underlying MHO lower amounts of ectopic fat (visceral and liver), and higher leg fat deposition, expandability of subcutaneous adipose tissue, preserved insulin sensitivity, and beta-cell function as well as better cardiorespiratory fitness compared to unhealthy obesity." (PMID 32128581, 2020). "However, excessive fat deposition in obesity leads to an unbalanced adipokine expression in adipocytes, resulting in metabolic syndromes such as insulin/leptin resistance." (PMID 33218042, 2020). "Furthermore, while bacterial LPS has been shown to impair insulin clearance, we recently demonstrated that members of the Enterobacteriaceae family compartmentalize in the tissues of those with T2D independently of obesity." (PMID 32860984, 2020). "Nevertheless, the mechanism of GIP-stimulated adipocyte lipolysis, rather than triglyceride storage, could potentially be an anti-obesity mechanism for pharmacological doses of GIPR agonists to overcome the anti-lipolytic effects of insulin." (PMID 33020469, 2020). "Overweight and obesity impact insulin signaling pathways (and β-cell insulin production)." (PMID 32599847, 2020). "Thus, next we will focus on three relevant hormones that orchestrate energy balance and play a critical role in obesity: leptin, ghrelin, and insulin." (PMID 33105762, 2020). "Moreover, mice (Sham and OVX) consuming HFD over the 12 week period display increased body weights, visceral adipose tissue weights, and circulatory concentrations of glucose and insulin, consistent with obesity-induced DM." (PMID 32635208, 2020). "Obesity leads to increased insulin secretion by beta-cells and a compensatory hyperinsulinemia." (PMID 31654312, 2020). "Given that FGF21 has been shown to improve insulin sensitivity and promote negative energy balance, some have suggested that obesity and associated metabolic syndrome represent an “FGF21-resistant” state." (PMID 32158768, 2020). "Turicibacter has also been associated with intestinal butyric acid, which could increase the secretion and sensitivity of insulin, and has significant anti-obesity and anti-inflammatory effects." (PMID 32231564, 2020). "The juice was also shown to enhance serum glucose and insulin levels in addition to adipokines, which suggested that it might improve obesity-induced metabolic diseases." (PMID 32325640, 2020). "In particular, it was observed that women with insulin resistance in comparision to insulin-sensitive women were at greater risk of developing breast cancer, regardless of BMI-defined obesity status." (PMID 33604295, 2020). "Hospitalized patients were older (68.0 ± 12.6 vs. 55.2 ± 12.6 years, p < 0.001), with more class III obesity (BMI ≥ 40 kg/m2, 9.7 vs. 3.5%, p = 0.03), hypertension (81.6 vs. 44.3%, p < 0.0001), insulin therapy (37% vs. 23.7%, p = 0.009), and lower SpO2 (91.6 vs. 97.3%, p < 0.0001) than outpatients." (PMID 33233575, 2020). "CB2 has also been detected in metabolic tissues, like adipose tissue and skeletal muscle and CB2 pharmacological or genetic inactivation in murine obesity models promote insulin-mediated glucose uptake in skeletal muscles, reduce adipose tissue inflammation, and thus improves insulin sensitivity." (PMID 33292302, 2020).
Obesity (continued). "In support of these clinical studies, a study from our group in low B12 pregnant women demonstrated that altered circulating micro-RNAs derived from adipose tissues could possibly mediate adipogenic and insulin-resistant phenotypes as a precursor to obesity." (PMID 32610503, 2020). "On the other hand, supplementation with NAD+ precursors or intermediates activates sirtuins and oxidative metabolism resulting in the protection against high-fat diet-induced obesity, improved glucose tolerance and hepatic insulin sensitivity, and lipid metabolism." (PMID 33414897, 2020). "In addition, dyslipidemia is also promoted in obesity, T2D and IR by a prolonged elevation of insulin levels." (PMID 32197513, 2020). "Girls with obesity presented a hormonal profile characterized by increased levels of circulating insulin (p < 0.0001), leptin (p < 0.0001), c-peptide (p < 0.0001), amylin (p = 0.0018), glucagon (p = 0.0195), and glucagon-like peptide-1 (GLP-1, p = 0.0001), relative to eutrophic controls." (PMID 33644105, 2020). "In addition, the number of pancreatic α-cells also increased under the insulin resistance condition of high fat diet-induced obesity." (PMID 33553143, 2020). "Thus, CSF has a potential to promote insulin sensitivity and even reduce obesity via beneficial regulation of the gut microecosystem." (PMID 32013093, 2020). "For instance, leptin and insulin typically rise with obesity and aging." (PMID 32499756, 2020). "Since CPA4 was associated with adipogenesis and insulin sensitivity, CPA4 may also participate in obesity-associated and diabetic cardiomyopathies." (PMID 32347291, 2020). "Consequently, obesity can result from genetic and epigenetic factors that influence body weight maintenance, in addition to an unbalanced glucose and insulin homeostasis." (PMID 32599690, 2020). "In conclusion, our data suggest blunted ADIPOQ signaling in obesity, may – besides its established impact on insulin signaling – further deteriorate metabolic function via circadian disruption of central metabolic control circuits." (PMID 32644041, 2020). "Obesity starting in the young age has deep consequences on the maturation of the pancreas innervation (density and intrinsic nervous system phenotype) and the nervous control of insulin secretion." (PMID 31922022, 2020). "Conditional disruption of neuronal cilia, either throughout the central nervous system or from pro-opiomelanocortin (POMC)-expressing cells in the hypothalamus, results in hyperphagic-related obesity in mice and is accompanied by elevated levels of serum insulin, glucose, and leptin." (PMID 33139642, 2020). "After androgen receptor knockdown in adipocytes in mice, the adipokine levels were altered, and the impaired insulin sensitivity and poor glucose tolerance were found not to be associated with obesity." (PMID 33488512, 2020). "This pathway has been demonstrated to have a vital role for maintaining energy homeostasis of adipocytes and its activation protect against HFD-induced obesity by inhibiting adipogenesis, gluconeogenesis, and stimulates lipolysis, glucose consumption, and insulin sensitivity." (PMID 32366215, 2020). "Furthermore, the hallmark systemic low-grade proinflammatory state that accompanies obesity has been described to contribute in part to insulin resistance in skeletal muscle (SkM) and in the liver, which compromises their normal metabolic functions." (PMID 32604889, 2020). "The results in the present study revealed that there are high significant differences in each BMI, WC, FBS, insulin, HOMA-IR, and HOMA-B2 between the normal weight group and obese group, suggesting that obesity has a role in impair of glucose-insulin homeostasis." (PMID 32952453, 2020).
Obesity (continued). "Several studies disclosed that an ablation of NLRP3 or of the inflammasome components ASC and caspase-1 in mice prevented obesity-induced inflammation in fat depots and liver, ameliorated insulin signaling, increased energy expenditure and prevented liver steatosis as well as pancreatic damage." (PMID 33178196, 2020). "Reducing levels of bacteria from the Firmicutes and Bacteroidetes phyla may improve insulin sensitivity in mice with diet-induced obesity." (PMID 33273482, 2020). "Additionally, the promoter site of ZPR1 binds peroxisome proliferator-activated receptor gamma (PPARG) proteins 1 and 2, which play a key role in insulin sensitivity and obesity." (PMID 31910446, 2020). "Additionally, individuals with obesity also presented increased quantities of insulin, leptin, and HOMA‐IR and lower levels of METs compared to normal weight subjects." (PMID 31968396, 2020). "Therefore, loss of TKT in adipose tissues alleviates high fat diet (HFD)-induced obesity, leading to reduced hepatic steatosis and improved insulin sensitivity." (PMID 32582032, 2020). "However, there are differences in the severity of the metabolic defects due to differences in the prevalence of obesity, as well as to racial/ethnic differences in insulin sensitivity." (PMID 32574161, 2020). "Even so, an acute awareness that multiple routes can converge on a single phenotype (e.g., obesity, adipose dysfunction, and insulin signalling impairment converge to produce signs of metabolic syndrome) should inform our design and interpretation of veterinary GWAS." (PMID 33233816, 2020). "Bacteroides acidifaciens has previously been proposed as a “lean bug” that could prevent obesity and improve insulin sensitivity." (PMID 33303854, 2020). "In contrast, adiponectin is down-regulated in obesity and improves insulin sensitivity." (PMID 32961883, 2020). "Further, there is a growing weight of evidence that fat distribution between the visceral and subcutaneous compartments may influence adipokine, insulin and cytokine regulation, and this is related to the development of obesity-related diseases." (PMID 32228685, 2020). "As HFD-induced obesity may also trigger alterations in the expression of genes involved in insulin signaling, lipogenesis, and gluconeogenesis, we sought to monitor the levels of representative transcripts relevant to these important metabolic processes." (PMID 33003580, 2020). "The results demonstrate that PEW could prevent HFD-induced obesity, and its related liver steatosis, insulin resistance and systemic inflammation by modulating the composition of gut microbiota." (PMID 32256675, 2020). "The impaired insulin signaling pathway may, therefore, as with leptin, contribute to the development of neuropsychiatric symptoms in the context of obesity." (PMID 32545890, 2020). "This compensatory response results in insulin hypersecretion and the development of hyperinsulinemia; in a vicious cycle, insulin circulates at levels higher than normal and therein participates in the metabolic dysregulations observed in obesity and T2DM." (PMID 32150819, 2020). "Chronic activation of the AMPKγ2 subunit in mice induces obesity and impairs insulin secretion." (PMID 32492936, 2020). "To investigate whether the differences in obesity development led to differences in insulin sensitivity and glucose tolerance, we performed glucose and insulin tolerance tests at week 10 and 11, respectively." (PMID 33022997, 2020). "Impaired insulin clearance triggers during obesity are ill-defined." (PMID 32860984, 2020). "Further to this, considering the possible up-stream role that hyperinsulinemia could be playing in MetS, treatments that reduce insulin secretion more directly may be beneficial, particularly early in obesity before it progresses to MUO." (PMID 32630256, 2020).